INS (insulin)
Diseases named in the same sentence as INS in open-access papers (continued):
Sharing a sentence is not in itself a finding about the gene and the disease.
Obesity (continued). "What is less clear is whether the obesity-induced adipose tissue inflammation leads to the increments in cytokine levels in blood plasma necessary to interfere with the action of insulin and to cause insulin resistance in muscle in vivo." (PMID 26661101, 2016). "Thus, our results document that plasma acylcarnitines and amino acids could serve as a gender-specific complex biomarker of propensity to obesity, however with a limited predictive value in case of the associated impairment of insulin sensitivity." (PMID 27183228, 2016). "Therefore, well-designed, prospective cohort studies are needed to address whether alterations of glucose and insulin level as well as obesity are interactively associated with elevated hsCRP level in the context of OSA in the future." (PMID 27684378, 2016). "We felt that this was important, as the VGF gene itself was found to be significant in a study related to sleep and brain development, but the available literature linked VGF with homeostatic processes, insulin secretion, and other metabolic functions that could be associated with obesity." (PMID 27088090, 2016). "Interestingly, the substitution of saturated by unsaturated fatty acids in the diet has beneficial effects on modulation of hypothalamic inflammation and function in obesity, underlying, at hypotalamic level, the interaction among insulin and/or leptin resistance, AMPK activation and hyperphagia." (PMID 27375435, 2016). "Our findings suggest that miR-4443 acts in a tumor-suppressive manner by down-regulating TRAF4 and NCOA1 downstream of MEK-C/EBP-mediated leptin and insulin signaling, and that insulin and/or leptin resistance (e.g. in obesity) may suppress this pathway and increase the risk of metastatic CRC." (PMID 27842582, 2016). "In addition, all main cancer risk factors confirmed in the study e.g., insulin use, HbA1c level and obesity heavily influence one another which may also confound the results." (PMID 27724912, 2016). "Studies are therefore lacking that assess whether important adverse metabolic changes that may increase the risk of T2DM and obesity, such as impaired insulin sensitivity, are associated with changes in the gut microbiome and associated SCFAs that could result from recurrent sleep loss." (PMID 27900260, 2016). "In addition, CD47 deficiency reduces obesity- associated metabolic complications including decreased systemic and adipose tissue inflammation and hepatosteatosis, and improved glucose tolerance and insulin sensitivity." (PMID 25747123, 2015). "Further work is required to explore these findings to establish whether circulating ECs may have a causal association with obesity and impaired glucose and insulin homeostasis or whether they are merely a marker of increased fat mass and associated metabolic dysregulation." (PMID 25874237, 2015). "However, in situations when other risk factors, i.e. immunosuppression, add to obesity, improving insulin sensitivity may be of help." (PMID 26398489, 2015). "For example, HFD and obesity have been shown to result in the accumulation of immune cells such as activated macrophages in adipose and liver tissue causing the secretion of pro-inflammatory cytokines that can directly impair insulin sensitivity in insulin target cells." (PMID 26448649, 2015). "Finally, I will explore how hypothalamic SIRT1 may be involved in age-associated weight gain and diet-induced obesity by regulating leptin and insulin sensitivity in the central nervous system." (PMID 26236282, 2015). "However, novel data indicate that obesity is associated with reduced brain insulin action." (PMID 25705204, 2015). "High-fat diet-induced obesity is associated with reduced brain insulin transport and an impairment of insulin action when given directly into the CNS, suggesting a loss of the effectiveness of insulin in the CNS to provide feedback signaling in circumstances of chronic hyperinsulinemia." (PMID 25705204, 2015).
Obesity (continued). "Phthalates might be implicated with obesity and insulin sensitivity." (PMID 25706863, 2015). "Observations regarding obesity could be due to confounding by common causes of both obesity and prostate cancer (e.g., calorie and dietary fat intake); the mitogenic hormones insulin and insulin-like growth factor-I; delayed detection in obese men; or a real biological effect." (PMID 26387087, 2015). "Moreover, resistance to insulin (IR), a hormone with anti-inflammatory action, is a hallmark of obesity-initiated metabolic syndrome, while inflammatory mediators additionally contribute to the IR state recognized in obesity." (PMID 26125190, 2015). "Obesity is associated with elevated production of insulin, which is a mitogenic factor that may also enhance tumor growth by increasing free insulin-like growth factor-I, which in turn modify cell proliferation, apoptosis and angiogenesis, and plays a role in bladder cancer." (PMID 25803438, 2015). "The loss of Acot7, Acot11/Them1, Acot13/Them2, and Acot15/Them5 result in phenotypes ranging from increased neurodegeneration to altered susceptibility to high-fat diet induced obesity, fatty liver, and insulin resistance through unknown mechanisms that unexpectedly altered whole body metabolism." (PMID 25760036, 2015). "We suggest that obesity-linked hypoxia may lead to similar alterations in brown adipocytes as in white fat cells – particularly changes in adipokine production, increased glucose uptake and lactate release, and insulin resistance." (PMID 25745415, 2015). "In addition, it should be mentioned that higher protein intake in infancy may increase later obesity risk, an effect that may be mediated through insulin and IGF-1." (PMID 25192029, 2014). "Therefore, impairing the insulin-CdsA feedback loop by genetic mutations or environmental conditions may cause an imbalance in fat storage, resulting in metabolic diseases such as obesity and related disorders." (PMID 24603715, 2014). "Indeed, low vitamin D alters insulin synthesis and secretion and is associated with obesity." (PMID 24699387, 2014). "The aim of the current study was to determine whether changes in insulin sensitivity resulting from maternal diet-induced obesity precede development of obesity in the offspring and if this was associated with changes in adipose tissue insulin signalling protein expression." (PMID 24749062, 2014). "Also, plausibility for a causal link between obesity and reproductive hormones can be found in studies that link modest weight loss and a reduction of central fat to improved insulin sensitivity, resulting in ovulation and pregnancy in overweight infertile women." (PMID 25763394, 2014). "Therefore, several mechanisms could explain the association of obesity and metabolic syndrome with prostate cancer pathogenesis, including sex steroid hormone, insulin and insulin-like growth factors and inflammation pathways." (PMID 24552491, 2014). "Moreover, we could not demonstrate any association of the other nine AGPAT6 variants with these traits of obesity, dyslipidemia, insulin sensitivity or insulin secretion." (PMID 24156295, 2013). "Moreover, serum from obese mice has been shown to induce an invasive phenotype in prostate cancer cell lines suggesting that metabolic changes associated with obesity (including elevated insulin) may drive metastatic transformation." (PMID 23573093, 2013). "Therefore, regular physical activity appears to act as a natural antioxidant and anti-inflammatory strategy for preventing obesity-associated complications: it improves glucose-insulin homeostasis, endothelial function and antioxidant defenses, while lowering circulating triglycerides." (PMID 23698776, 2013).
Obesity (continued). "Data suggest that the pharmacological targeting of ME1 or the inclusion of soy protein in the diet may provide avenues to reduce obesity and its associated pro-tumorigenic endocrine environment and improve insulin sensitivity, potentially disrupting the obesity-colon cancer connection." (PMID 23056418, 2012). "Furthermore, GIP may be directly implicated in fat metabolism and development of obesity by influencing insulin sensitivity of adipocytes." (PMID 22619730, 2012). "Prolonged liver oxidative stress in human obesity is associated with development of a wide disease spectrum ranging from steatosis to steatosis with inflammation, fibrosis, and cirrhosis (nonalcoholic steatohepatitis), a redox imbalance showing a functional interdependency with insulin resistance." (PMID 23304111, 2012). "Since we previously found that AMPK activation directly down-regulates macrophage inflammation, a major source of adipose inflammation, we explored whether AICAR’s beneficial effects on insulin sensitivity were associated with suppressions of obesity-induced inflammation." (PMID 23183898, 2012). "Thus, alterations of insulin levels and insulin-mediated signals/transcription might be an interesting candidate to explain the association of obesity and dementia." (PMID 22654904, 2012). "However, the fact that we detect association between the Adv36-ELISA-signal and the clinical phenotypes of obesity and insulin sensitivity similar to the associations with these variables found in previous studies strongly suggests that the Adv36-ELISA indeed measures prior Adv36 infection." (PMID 22848557, 2012). "It is therefore plausible that in the context of diet- or obesity-induced fatty liver associated with excessive n-6/n-3 ratio, hepatic eicosanoid production is tilted towards proinflammatory components and participates to proinflammatory and insulin resistant status aggravating the MetS." (PMID 21197079, 2011). "It is known that endurance exercise training could lead to fiber type transformation, mitochondrial biogenesis, angiogenesis and other adaptive changes in skeletal muscle, thus further enhancing fat oxidation that is associated with improvement of insulin sensitivity in obesity." (PMID 21887385, 2011). "In view of the observations that OT-deficient mice, known to develop late-onset obesity, also exhibit decreased insulin sensitivity and impaired glucose tolerance, we determined whether chronic central OT infusion would affect these parameters in HFD-induced obese rats." (PMID 21980491, 2011). "Moreover, the associationbetween obesity as well as type II diabetes and the antidiabeticeffect of TZDs fuel the hypothesis that PPARγactivity in adipocytes is a key to systemic insulin sensitivity." (PMID 17389768, 2007). "Furthermore, it raises the concern that the obesity caused by the combination of a high-carbohydrate diet and insulin may have contributed to the patient's failing kidney function." (PMID 16774676, 2006). "Metabolic conditions such as obesity and IR enhance renal UA reabsorption through insulin‐mediated effects on URAT1 and GLUT9." (PMID 41521685, 2026). "There was substantial heterogeneity in inclusion criteria, ranging from individuals who were newly diagnosed, insulin therapy, experiencing severe hypoglycaemia, or living with obesity." (PMID 41277464, 2026). "GLP‐1 receptor agonists (GLP‐1 RAs), such as liraglutide, semaglutide and tirzepatide, were developed to treat obesity as they promote satiety, delay gastric emptying and enhance glucose‐dependent insulin secretion." (PMID 41048008, 2026). "Background/Objectives: Obesity is characterized by dysregulated hypothalamic energy homeostasis and reduced central responsiveness to the anorexigenic hormones leptin and insulin." (PMID 41754099, 2026). "For TGIF1, DNA methylation levels were increased in subcutaneous adipose tissue (N = 219) of children with obesity and correlated with fasting serum insulin concentrations." (PMID 42304432, 2026).
Obesity (continued). "Selective depletion of septal ATMs enhanced beige fat formation, increased energy expenditure, conferred resistance to diet-induced obesity, and improved glucose and insulin responses." (PMID 41551882, 2026). "This nanoplatform achieved efficient gene silencing in adipose tissue and, in HFD-induced type 2 diabetes mouse model, significantly improved both obesity and insulin sensitivity." (PMID 41551882, 2026). "Strikingly, zygotic microinjection of synthetic 28S-rsRNAs recapitulated paternal immune activation phenotypes, resulting in offspring exhibiting metabolic syndrome-like phenotypes, including obesity and impaired insulin sensitivity." (PMID 41536523, 2026). "We recently demonstrated that three months of high-dose (4 g/daily) ω-3PUFA (fish oil, FO) supplementation improved insulin sensitivity, and decreased systemic and AT inflammation in individuals with obesity (BMI ≥ 30 kg/m2)." (PMID 41972668, 2026). "Taken together, our findings establish macrophage GPX4 as a key regulator of metabolic inflammation, lipid homeostasis, and insulin sensitivity in the context of obesity." (PMID 41524084, 2026). "This chronic low-grade inflammation in obesity disrupts brain homeostasis, leading to oxidative stress, inflammation, altered hormones, insulin resistance, and blood-brain barrier (BBB) compromise." (PMID 41543809, 2026). "The loss of subcutaneous fat in lipodystrophies mirrors the ‘adiposopathy’ and limited expandability of the same depot in obesity, turning into ectopic lipid deposition, lipotoxicity and insulin resistance development." (PMID 41597651, 2026). "PGC-1α counteracts obesity by enhancing mitochondrial biogenesis, increasing fatty acid oxidation, and promoting thermogenesis, all of which collectively improve insulin sensitivity and reduce adipose tissue inflammation." (PMID 41596403, 2026). "We demonstrate that deletion of hepatocyte-specific α-Parvin had only minimal influence on obesity-induced liver or whole-body insulin resistance." (PMID 41577027, 2026). "Mechanistically, type I inflammatory cytokines and obesity-associated molecules—including IFN-γ, TNF, leptin, insulin, and palmitate—induced PD-1 expression on macrophages through mTORC1- and glycolysis-dependent pathways." (PMID 41551882, 2026). "We present the case of a 69-year-old man with stage IV chronic obstructive pulmonary disease (COPD) on chronic oxygen, T2DM on insulin, and class II obesity (reference range, body mass index [BMI], 35.0-39.9) who underwent pre-lung transplant evaluation." (PMID 41928866, 2026). "We further discuss IGFBP2 within an autocrine, paracrine, and endocrine framework, with emphasis on its effects on glucose handling, lipid metabolism, insulin sensitivity, and metabolic adaptation in obesity-related disease states." (PMID 42095224, 2026). "Although postprandial IL-1β can be physiologically supportive of insulin secretion and glycemic control, its persistent elevation in obesity shifts from adaptive to maladaptive, contributing to β-cell secretory exhaustion and dysglycemia." (PMID 41516407, 2026). "Background/Objectives: Insulin-Resistant Normal Weight and Insulin-Sensitive Obesity are atypical cardiometabolic phenotypes whose clinico-biological features, management, and prognosis are a subject of extensive scientific debate." (PMID 41745574, 2026). "Together, these findings indicate that central irisin administration attenuates obesity-related hypothalamic inflammation and modulates central insulin signaling, supporting a role for irisin as a regulator of neuroinflammation-linked metabolic dysfunction." (PMID 41748769, 2026). "In this study, zygotic microinjection of a synthesized 28S-rsRNAs pool recapitulated paternal immune activation phenotypes, resulting in offspring exhibiting metabolic disorders, including obesity and impaired insulin sensitivity." (PMID 41536523, 2026).
Obesity (continued). "The secretion of pro-inflammatory cytokines from adipose tissue (AT) is increased during obesity, contributing to the impairment of systemic insulin sensitivity." (PMID 41972668, 2026). "This study investigated the anti-inflammatory, anti-obesity, and insulin-sensitizing effects of a 40% ethanol extract of C." (PMID 42279645, 2026). "This narrative review aims to systematically synthesize evidence on non-pharmacological naturopathic treatments (yoga, hydrotherapy, diet, and acupuncture) for improving insulin sensitivity, reducing obesity, and alleviating PCOS symptoms." (PMID 41853396, 2026). "Abstract figure legend Maternal obesity induces systemic inflammation and high insulin and leptin levels, potentially promoting hepcidin release into circulation and thus iron sequestration in specific tissue compartments." (PMID 41275403, 2026). "Global deletion of the ubiquitin ligase seven in absentia homolog 2 (SIAH2) improves glucose tolerance and insulin sensitivity while reducing adipose tissue inflammation with obesity." (PMID 41690475, 2026). "In patients with obesity, insulin levels were not only significantly higher than in the control group, but insulin also showed a positive, statistically significant effect on both systolic and diastolic blood pressure." (PMID 41596212, 2026). "The functional roles of several miRNAs in obesity and related disorders have been reported to involve adipocyte differentiation, fat metabolism, or insulin signaling." (PMID 41532014, 2026). "Our study exclusively used male mice, which are more prone to obesity‐induced cardiometabolic dysfunction, including robust visceral adiposity, insulin resistance and RAAS activation, compared with females." (PMID 41042601, 2026). "Chronic low‐grade systemic inflammation induced by obesity impairs insulin signaling, disrupts glucose homeostasis, and contributes to insulin resistance and systemic metabolic dysfunction." (PMID 41524084, 2026). "In adolescents with obesity, NC positively correlated with fasting insulin, HOMA-IR, triglycerides, systolic blood pressure, and PsiMS score (p < .05 for all)." (PMID 42087115, 2026). "Here, it was demonstrated that participants with obesity receiving an FMT from lean volunteers showed significant improvement in insulin sensitivity." (PMID 40587382, 2026). "Most participants were male, 23% and 53% suffered from obesity, and 39% and 58% were categorized as insulin resistant, respectively." (PMID 41492318, 2026). "The results showed that macrophage‐specific deletion of Gpx4 attenuated HFD‐induced obesity and improved insulin sensitivity in mice in vivo." (PMID 41524084, 2026). "Over the past 25 years, Foxo1 has evolved from a liner insulin effector to a pleiotropic integrator of systemic metabolic stress during obesity and aging." (PMID 41597184, 2026). "Comparative effectiveness against other antidiabetic agents: Several studies have highlighted that GLP-1RAs reduce the risk of obesity-related cancers, including HCC, compared with insulin use." (PMID 41607999, 2026). "Lipodystrophies are rare syndromes characterized by partial or complete loss of subcutaneous adipose tissue leading to ectopic lipid deposition, insulin resistance, and the same metabolic derangements observed in obesity." (PMID 41597651, 2026). "These adipokines regulate energy balance, blood pressure, insulin sensitivity, and inflammatory responses and directly or indirectly contribute to the development of obesity‐related metabolic diseases." (PMID 41524288, 2026). "This pathway is known to be activated under conditions of obesity because mitochondrial DNA leaks into the cytoplasm, which drives chronic inflammation and insulin resistance." (PMID 41601924, 2026). "Elevated SUA levels can lead to IR, liver fat accumulation, and inflammation in adipose tissue, while metabolic issues—mainly obesity and high insulin levels—can decrease the renal clearance of UA, reinforcing hyperuricemia." (PMID 41521685, 2026).